CFTR (CF transmembrane conductance regulator)
Diseases named in the same sentence as CFTR in open-access papers (continued):
Sharing a sentence is not in itself a finding about the gene and the disease.
cystic fibrosis (continued). "While dysfunction of ClC channels has been implicated in diverse cancers, the role of CFTR in cancer risk is particularly notable in the context of cystic fibrosis —a multisystem genetic disorder caused by mutations in the CFTR gene." (PMID 41155636, 2025). "Cystic fibrosis, caused by genetic mutations in the cystic fibrosis transmembrane conductance regulator (CFTR) protein, affects over 30,000 individuals in the United States." (PMID 39881848, 2025). "Cystic fibrosis is a genetic disorder caused by mutations in the CFTR gene, leading to impaired CFTR function, mucus accumulation, chronic infections, and inflammation." (PMID 41253756, 2025). "Cystic fibrosis is the most common autosomal recessive lethal disorder worldwide caused by mutations in the CF transmembrane conductance regulator (CFTR) gene, which represents conditions with variable expressivity and penetrance." (PMID 41431510, 2025). "Background and Objectives: Cystic fibrosis, caused by CFTR gene mutations, primarily affects the respiratory and gastrointestinal systems." (PMID 40142300, 2025). "CFTR modulators target the underlying cause of cystic fibrosis by improving CFTR function systemically, including in the lungs and sweat glands." (PMID 39756425, 2025). "The nonsense variant rs74767530 in CFTR results in a termination of the amino acid chain at position 1162 and is considered pathogenic for cystic fibrosis according the ClinVar classification." (PMID 40428425, 2025). "Cystic fibrosis is an autosomal recessive genetic disorder caused by mutations in the cystic fibrosis transmembrane conductance regulator (CFTR) gene, identified in 1989." (PMID 41462739, 2025). "Mutations in the CFTR gene, the molecular basis of cystic fibrosis, disrupt epithelial ion transport and profoundly alter the gastrointestinal environment." (PMID 41009994, 2025). "While the nonsense variant in CFTR is classified as pathogenic for cystic fibrosis in ClinVar, the other CFTR missense variant in the proband has a classification of benign/likely benign." (PMID 40428425, 2025). "CFTR encodes the cystic fibrosis transmembrane regulator and is best known for its association with cystic fibrosis, a condition characterized by impaired water and ion secretion." (PMID 40428425, 2025). "Cystic fibrosis is a life‐threatening condition caused by pathogenic mutations of the cystic fibrosis transmembrane conductance regulator (CFTR) anion channel." (PMID 40785054, 2025). "Cystic fibrosis is a rare autosomal‐recessive disorder caused by CFTR (CF transmembrane conductance regulator) chloride channel gene mutation with disrupted chloride secretion." (PMID 41347296, 2025). "Biallelic CFTR variants cause cystic fibrosis (OMIM #219700), in which cystic fibrosis-related diabetes (CFRD) develops in 40–50% of affected adults, characterized by both insulin deficiency and insulin resistance." (PMID 41153735, 2025). "Here, we focus on two case studies: the CFTR protein, which is responsible for chloride ion flux and whose mutations cause cystic fibrosis, and the transmembrane protein YddG, which is found in bacteria and is involved in the export of aromatic amino acids." (PMID 40220324, 2025). "Cystic fibrosis is an autosomal, recessive, multi-organ disease caused by variants in the cystic fibrosis transmembrane conductance regulator (CFTR) anion channel." (PMID 39655913, 2025). "Cystic fibrosis is an autosomal recessive disorder caused by a genetic mutation in the cystic fibrosis transmembrane conductance regulator (CFTR) gene on chromosome 7, which encodes for a chloride ion transporter on the apical surface of epithelial cells." (PMID 41464737, 2025). "Cystic Fibrosis is a life-shortening, multi-organ disease caused by mutations in the CF transmembrane conductance regulator (CFTR) gene." (PMID 40141278, 2025). "Cystic fibrosis is a common monogenic multisystem disease caused primarily by variants in the CFTR gene." (PMID 40182926, 2025).
cystic fibrosis (continued). "By correcting the F508del mutation, we aim to address the genetic cause of Cystic Fibrosis and restore CFTR function." (PMID 41416220, 2025). "In individuals with cystic fibrosis, mutations in the CFTR gene impair ion transport and mucus hydration, thereby altering the intestinal microenvironment at the epithelial surface." (PMID 41009994, 2025). "Cystic fibrosis is a rare genetic condition marked by mutations in the cystic fibrosis transmembrane conductance regulator (CFTR) chloride channel within epithelial cells." (PMID 40519270, 2025). "For example, the NMD pathway involved in the cystic fibrosis transmembrane conductance regulator (CFTR) gene amplifies the effects of nonsense mutations associated with cystic fibrosis." (PMID 40862762, 2025). "For example, a pathogenic variant in the Cystic Fibrosis Transmembrane Conductance Regulator (CFTR) protein causing cystic fibrosis has been considered a target for a potential therapy with sodium phenylbutyrate." (PMID 41163474, 2025). "The patient was diagnosed with cystic fibrosis at age of 3 following identification of a heterozygous mutation in the cystic fibrosis transmembrane conductance regulator (CFTR) gene." (PMID 40933694, 2025). "Cystic fibrosis is a genetic disease caused by mutations in the CFTR gene, which encodes the ion channel protein, cystic fibrosis transmembrane conductance regulator." (PMID 39415058, 2025). "Mutations in the CFTR gene cause cystic fibrosis, and cystic fibrosis transmembrane conductance regulators play a role in water and ion transport across the corneal endothelium." (PMID 40864823, 2025). "Cystic fibrosis is an autosomal recessive disorder caused by mutations in the CFTR gene (cystic fibrosis transmembrane conductance regulator)." (PMID 41148816, 2025). "Conversely, and of great interest in proposing “miRNA Therapeutics” for cystic fibrosis, the treatment of target epithelial cells with inhibitors of miRNAs down-regulating CFTR is associated with the hyperactivation of CFTR gene expression." (PMID 39846681, 2025). "The coexistence of trisomy 21 and cystic fibrosis is extremely rare, with fewer than 10 reported cases, all involving homozygous CFTR mutations." (PMID 40241998, 2025). "Abstract figure legend Molecular pathomechanisms of five rare cystic fibrosis‐associated mutations of the cystic fibrosis transmembrane conductance regulator (CFTR) anion channel." (PMID 40785054, 2025). "Cystic Fibrosis, caused by mutations in the CF transmembrane conductance regulator (cftr) gene, affects approximately one in 3,400 newborns of Caucasian descent in the US." (PMID 40508114, 2025). "Among the best studied disease-causing secretion defects from biosynthetic organelles are mutations in the cystic fibrosis transmembrane conductance regulator (CFTR)." (PMID 40735229, 2025). "The challenges associated with NPC1I1061T misfolding and trafficking defects share remarkable parallels with other disorders involving mutant proteins, such as cystic fibrosis caused by defective cystic fibrosis transmembrane conductance regulator (CFTR)." (PMID 40516874, 2025). "Cystic Fibrosis is an autosomal recessive genetic condition caused by variants in the CFTR gene, marked by disease in the lungs, pancreas, sinuses, and gastrointestinal tract." (PMID 40843902, 2025). "As a result, the normal CFTR Cl-channels in the cell membrane are significantly reduced and can lead to a disease-causing cystic fibrosis phenotype." (PMID 40182926, 2025). "Elexacaftor/Tezacaftor/Ivacaftor (ETI) therapy has significantly improved clinical outcomes in people with cystic fibrosis (PwCF) carrying at least one Phe508del CFTR mutation." (PMID 41039909, 2025). "Pathogenic variants in the cystic fibrosis transmembrane conductance regulator (CFTR) gene cause cystic fibrosis, a genetic multisystem disease primarily characterized by severe respiratory disorder." (PMID 40806745, 2025).
cystic fibrosis (continued). "Patients with cystic fibrosis have dysfunctional cystic fibrosis transmembrane conductance regulator (CFTR), and this predisposes them to NTM infection." (PMID 40372084, 2025). "Cystic fibrosis is a chronic, autosomal-recessive disorder caused by mutations in the CFTR gene, leading to thickened secretions that affect multiple organ systems." (PMID 40559180, 2025). "NCT02649751 tested (R)-roscovitine in patients suffering from cystic fibrosis, bearing the most common F508del CFTR mutation." (PMID 41205263, 2025). "Cystic fibrosis is an autosomal recessive genetic disorder caused by mutations in the cystic fibrosis transmembrane conductance regulator (CFTR) gene, affecting over 89,000 individuals worldwide." (PMID 41244782, 2025). "In humans, CFTR function is directly measured by a sweat test, which is the gold standard diagnostic test for cystic fibrosis." (PMID 40333927, 2025). "A dysfunctional CFTR channel, as seen in patients with cystic fibrosis, causes an altered intestinal milieu due to decreased bicarbonate and water secretion." (PMID 41146523, 2025). "Cystic fibrosis is a genetic disorder caused by a mutation in the cystic fibrosis transmembrane conductance regulator (CFTR) gene and roughly affects over 40,000 people in the United States." (PMID 40806586, 2025). "For infertile men with CFTR variants, protocols require CFTR carrier screening and genetic counseling for female partners, since children have 50% cystic fibrosis risk if the mother is a carrier." (PMID 40951413, 2025). "Cystic Fibrosis is a monogenic genetic disease caused by mutations in the Cystic Fibrosis Transmembrane conductance Regulator (CFTR) chloride/bicarbonate channel, which is expressed in certain epithelia cells." (PMID 40631082, 2025). "Here, the authors apply an in vivo structural method to uncover how Cystic Fibrosis-causing CFTR variants misfold, respond to current therapies and uncover an activation mechanism previously missed." (PMID 41258017, 2025). "In patients with symptoms suggestive of cystic fibrosis, genetic testing, specifically a DNA test for 38 CFTR gene mutations and/or CFTR sequencing, is crucial for confirming the diagnosis." (PMID 40806984, 2025). "Cystic fibrosis is a genetic disorder resulting from mutations to the CF transmembrane regulator (CFTR) anion channel." (PMID 40688096, 2025). "Mutations in the CFTR gene, which cause the autosomal recessive disease cystic fibrosis, can also affect male fertility." (PMID 40724872, 2025). "Cystic fibrosis is a monogenic disease caused by mutations in the cystic fibrosis transmembrane conductance regulator (CFTR) gene, which encodes a Cl−/HCO3− ion channel located at the apical plasma membrane (PM) of epithelial cells." (PMID 40910003, 2025). "Previously, we developed a hierarchical graph-theoretic model to investigate the effects of point mutations on the NBD2 domain of the CFTR protein, which is implicated in cystic fibrosis." (PMID 41359941, 2025). "Fanen P., Wohlhuter-Haddad A., Hinzpeter A. Genetics of cystic fibrosis:CFTR mutation classifications toward genotype-based CFtherapies." (PMID 40297296, 2025). "Cystic fibrosis is a rare genetic disease in which mutations in the gene encoding for the CF transmembrane conductance regulator protein result in a multisystem disease." (PMID 40221761, 2025). "In this regard, the basal cells of the lung should be considered the main target for the correction of a mutation in the case of cystic fibrosis because they are the source of all other types of lung cells, including CFTR-expressing epithelial cells." (PMID 40299508, 2025). "Cystic fibrosis is a life-threatening disorder caused by mutations in the CFTR gene, leading to defective chloride ion transport and thickened mucus in the respiratory and gastrointestinal systems." (PMID 40363673, 2025).
cystic fibrosis (continued). "Here, we systematically evaluated 12 modifications of the PEmax system for correcting the CFTR F508del pathogenic variant that caused cystic fibrosis in patient-derived airway basal cells." (PMID 40869263, 2025). "Cystic Fibrosis is an autosomal recessive genetic disorder caused by variants in the gene encoding the cystic fibrosis transmembrane conductance regulator (CFTR) protein." (PMID 40217771, 2025). "Cystic fibrosis is an autosomal recessive genetic disorder caused by mutations in the gene encoding the CF transmembrane conductance regulator (CFTR) protein." (PMID 40144660, 2025). "The aim of the review is to present the complex relationships between the presence of CFTR gene mutations and the gut microbiota dysbiosis in patients with cystic fibrosis." (PMID 41009994, 2025). "While primarily associated with cystic fibrosis, CFTR abnormalities can indirectly influence pain pathways by promoting chronic inflammation and epithelial dysfunction, leading to altered pain sensitivity and management." (PMID 40313396, 2025). "CFTR modulators have revolutionized the treatment landscape for cystic fibrosis CF by targeting specific genetic mutations and restoring defective CFTR protein function." (PMID 40842499, 2025). "This approach identified a homozygous rare variant, c.1375_1383del in the CFTR gene, confirming the diagnosis of cystic fibrosis." (PMID 40933696, 2025). "Cystic fibrosis is an autosomal recessive genetic disorder caused by mutations in the CF transmembrane regulator (CFTR) protein, which leads to altered ion and fluid transport across epithelial membranes in multiple organ systems." (PMID 40483244, 2025). "In cystic fibrosis, the common F508del mutation results in a misfolded CFTR protein retained and targeted for degradation in the ER, preventing it from reaching its functional site at the plasma membrane." (PMID 40516874, 2025). "Previous studies have demonstrated that mTOR inhibitors reduce inflammation in cystic fibrosis 80–82, while reduced ubiquitin-mediated proteolysis has been linked to decreased inflammation and increased CFTR cell surface expression." (PMID 40501816, 2025). "have gained attention as emerging opportunistic pathogens in cystic fibrosis, a genetic disorder caused by mutations in the cystic fibrosis transmembrane conductance regulator (CFTR) gene." (PMID 40137756, 2025). "The aim of our review is to present the complex relationships between the presence of CFTR gene mutations and the composition and activity of the gut microbiota in patients with cystic fibrosis." (PMID 41009994, 2025). "The phenotypic variability and severity of cystic fibrosis are influenced by several factors beyond CFTR gene mutations, including age, disease progression, environmental factors, and modifier genes." (PMID 40806984, 2025). "Cystic fibrosis is an autosomal-recessive, chronic, progressive, multi-system disorder caused by mutations in the CFTR (cystic fibrosis transmembrane conductance regulator) gene." (PMID 40559180, 2025). "Cystic fibrosis is a chronic, progressive, multi-organ disease due to the presence of pathogenic variants in both alleles of the Cystic Fibrosis Transmembrane Conductance Regulator (CFTR) gene, which encodes a homonymous protein." (PMID 40564735, 2025). "Cystic fibrosis is a rare autosomal recessive disorder caused by mutations in the cystic fibrosis transmembrane conductance regulator (CFTR) gene, leading to defective chloride and bicarbonate transport across the apical membrane of epithelial cells." (PMID 41039909, 2025). "To date, 2121 CFTR variants have been reported in the Cystic Fibrosis Mutations Database, their distribution and frequency varying by region and ethnic group." (PMID 40806984, 2025). "In cystic fibrosis, mutations in the cystic fibrosis transmembrane conductance regulator (CFTR) alter lipid metabolism and are associated with excess CHOL accumulation." (PMID 40943244, 2025).
cystic fibrosis (continued). "Pathogenic variants in the CFTR gene, associated with cystic fibrosis, were the fifth most common, with a carrier frequency of 3%, while CF is one of the most common monogenic diseases in Russia, with well-established AF." (PMID 41595422, 2025). "CFTR modulators have significantly affected the prognosis for cystic fibrosis, improving the clinical course in most patients with the F508del variant and several other CFTR gene variants." (PMID 41373889, 2025). "Cystic fibrosis is an autosomal recessive disease that is caused by mutations in the Cystic Fibrosis Transmembrane Conductance Regulator (CFTR) gene." (PMID 39931243, 2025). "Cystic fibrosis, for example, arises when both copies of a patient’s CFTR gene are compromised due to potentially different variants inherited from each parent." (PMID 39825393, 2025). "Cystic Fibrosis, a multi-organ disease stemming from CFTR gene mutations, is characterized by progressive pulmonary disease, chronic inflammation, and a pro-oxidative environment." (PMID 40740993, 2025). "Cystic fibrosis is an autosomal recessive disease caused by several pathogenic variants in the CFTR gene." (PMID 40869263, 2025). "Cystic fibrosis is caused by pathogenic variants in the cysticfibrosis transmembrane conductance regulator (CFTR)gene." (PMID 40297296, 2025). "We aimed to evaluate the comparative efficacy and safety of CFTR modulators for people with cystic fibrosis who have a phe508del mutation." (PMID 41377908, 2025). "Recent advances in cystic fibrosis screening illustrate this progress, as expanded CFTR variant panels and next-generation sequencing now support more inclusive and timely detection, moving toward primary genetic screening." (PMID 41399729, 2025). "Cystic fibrosis is an autosomal recessive disease caused by mutations in the CFTR gene, which encodes a chloride and bicarbonate channel essential for airway hydration and epithelial homeostasis." (PMID 41446468, 2025). "In 2017, the US FDA extended the approval of the Vertex Pharmaceuticals’ cystic fibrosis drug ivacaftor (CFTR modifier) to a broader range of mutations, based solely on in vitro data." (PMID 39931243, 2025). "Cystic fibrosis, caused by mutations in the cystic fibrosis conductance regulator (CFTR) gene, is the most common rare disease affecting the Caucasian population, with an incidence of 2,500–3,500 newborns." (PMID 40740993, 2025). "Cystic fibrosis is a genetic disorder that is caused by a mutation in the Cystic Fibrosis Transmembrane Conductance Regulator gene (CFTR), resulting in the dysfunction of the chloride channel." (PMID 40856881, 2025). "Cystic fibrosis is a severe and progressive, inherited, multisystem disorder primarily caused by mutations in the cystic fibrosis transmembrane conductance regulator (CFTR) gene." (PMID 40981163, 2025). "Cystic fibrosis is a progressive, multi‐system genetic disorder caused by mutations in the cystic fibrosis transmembrane conductance regulator (CFTR) gene." (PMID 40923683, 2025). "Cystic fibrosis is an autosomal recessive genetic disorder caused by mutations in the cystic fibrosis transmembrane conductance regulator (CFTR) gene, with a poor prognosis." (PMID 40351459, 2025). "Of the more than 2,100 identified variants in the CFTR gene, over 1,000 are associated with CFTR dysfunction, which is the hallmark of cystic fibrosis." (PMID 41158800, 2025). "The most common CFTR mutation that causes cystic fibrosis (F508del) prevents maturation from an immature core glycosylated state to the complex form over time, but in contrast to KCC2, F508del CFTR is delivered to the ERAD pathway." (PMID 40074080, 2025). "CFTR encodes a chloride channel implicated in cystic fibrosis pathogenesis and cholesterol trafficking." (PMID 40817859, 2025). "Cystic fibrosis is an autosomal-recessive genetic disorder caused by mutations in the CF transmembrane conductance regulator (CFTR) gene, which normally produces a secretory anion channel protein." (PMID 40142867, 2025).